ENSG00000273217 (novel protein)
Gene: Protein-coding gene on chromosome 5 (131,425,891 to 131,796,983, reverse strand). Ensembl gene ENSG00000273217.
Genetic constraint (gnomAD): Loss-of-function variants: 54 observed, 161.89 expected, observed/expected ratio (o/e) 0.33, 90% interval 0.27 to 0.42. Missense variants: 1,616 observed, 1,906.4 expected, observed/expected ratio (o/e) 0.85, 90% interval 0.81 to 0.88. Synonymous variants: 658 observed, 648.68 expected, observed/expected ratio (o/e) 1.01, 90% interval 0.95 to 1.08.